LTBR (lymphotoxin beta receptor)
Description:
Receptor for the heterotrimeric lymphotoxin containing LTA and LTB, and for TNFS14/LIGHT. Activates NF-kappa-B signaling pathway upon stimulation with lymphotoxin (LTA(1)-LTB(2)). Promotes apoptosis via TRAF3 and TRAF5. May play a role in the development of lymphoid organs.
Synonyms: D12S370; TNFCR; TNFR3; TNFRSF3; TNFR-RP; TNFR2-RP; TNF-R-III; LT-BETA-R
Tractability: Antibody: a drug acting on it is in phase 1 trials; its Gene Ontology location is reachable by antibodies, with high confidence; UniProt predicts a signal peptide or a membrane-spanning region. PROTAC: ubiquitination databases record sites on it.
Target class: Membrane receptor
Gene: Protein-coding gene on chromosome 12 (6,375,045 to 6,391,571, forward strand). Ensembl gene ENSG00000111321.
Subcellular location: Membrane
Subcellular location (Human Protein Atlas): Golgi apparatus
Pathways (Reactome):
Immune System: TNF receptor superfamily (TNFSF) members mediating non-canonical NF-kB pathway; TNFR2 non-canonical NF-kB pathway
Gene Ontology:
Molecular function: identical protein binding; protein binding; ubiquitin protein ligase binding
Biological process: cellular response to mechanical stimulus; positive regulation of canonical NF-kappaB signal transduction; positive regulation of extrinsic apoptotic signaling pathway; positive regulation of JNK cascade; activation of NF-kappaB-inducing kinase activity; apoptotic process; dendritic cell homeostasis; regulation of necroptotic process; regulation of type I interferon production; signal transduction; T cell activation; hematopoietic or lymphoid organ development; immune response
Cellular component: Golgi apparatus; plasma membrane; tumor necrosis factor receptor superfamily complex; membrane
Genetic constraint (gnomAD): Loss-of-function variants: 16 observed, 48.47 expected, observed/expected ratio (o/e) 0.33, 90% interval 0.22 to 0.5. The upper end of that interval is the gene's LOEUF score, 0.5, which puts it in group 2 of 6, group 1 being the genes least tolerant of losing a copy. Missense variants: 431 observed, 544.22 expected, observed/expected ratio (o/e) 0.79, 90% interval 0.73 to 0.86. Synonymous variants: 223 observed, 222.62 expected, observed/expected ratio (o/e) 1, 90% interval 0.9 to 1.12.
Homologues: Orthologues: chimpanzee LTBR (98% identical), macaque LTBR (93% identical), pig LTBR (72% identical), rabbit LTBR (71% identical), dog LTBR (70% identical), guinea pig LTBR (67% identical), mouse Ltbr (65% identical), rat Ltbr (57% identical), zebrafish tnfrsf1b (17% identical), zebrafish tnfrsf11a (17% identical), zebrafish hdr (16% identical), zebrafish cd40 (14% identical), and 3 more. Paralogues in human: TNFRSF1B (20% identical), TNFRSF21 (19% identical), TNFRSF11A (19% identical), CD40 (19% identical), TNFRSF8 (18% identical), TNFRSF1A (16% identical), NGFR (15% identical), TNFRSF6B (15% identical), TNFRSF14 (14% identical), TNFRSF11B (14% identical), TNFRSF4 (14% identical), RELT (13% identical), and 9 more.
Diseases named in the same sentence as LTBR in open-access papers:
LTBR is named in the same sentence as 149 diseases in open-access papers, as found by Europe PMC text mining. Sharing a sentence is not in itself a finding about the gene and the disease. The quoted sentences say what the papers report.
autoimmune disease (12 papers, 2009 to 2024). A disorder resulting from loss of function or tissue destruction of an organ or multiple organs, arising from humoral or cellular immune responses of the individual to their own tissue constituents. "The lymphotoxin-beta receptor (LTBR) pathway has been associated with the appearance of ELSs at sites of chronic inflammation in a variety of autoimmune diseases, and has been shown to regulate the expression levels of CXCL13, CCL19, and PNAd." (PMID 38736890, 2024). "The pleiotropic functions of lymphotoxin (LT)β receptor (LTβR) signaling are linked to the control of secondary lymphoid organ development and structural maintenance, inflammatory or autoimmune disorders, and carcinogenesis." (PMID 33805271, 2021). "The lymphotoxin-beta receptor (LTBR) pathway has been associated with the presence of TLT (or ectopic follicles) at sites of chronic inflammation in several autoimmune diseases." (PMID 22044682, 2011). "The peptides which selectively inhibit each arm of LTβR signaling may help us explore mechanisms underlying the complex signaling network, and serve as precision medicine against autoimmune diseases and cancer." (PMID 33805271, 2021). "Of note, LTβR signaling has been shown to be involved in the pathogenesis of many human diseases, not only cancer but also several autoimmune diseases such as, e.g., diabetes." (PMID 39215104, 2024). "For some regions, we found suggestive novel associations that have prior evidence of association with autoimmune disease, such as TEC, a tyrosine kinase involved in T cell signalling and activation, and LTBR, a signalling receptor expressed on myeloid cells." (PMID 36580032, 2023). "Multiple strategies have been developed to dampen or boost LTβR signaling in various cell types to attenuate autoimmune diseases/inflammation or cancer immunity, respectively." (PMID 33805271, 2021). "LTβR-Ig has been shown to alleviate various autoimmune diseases in mouse models of rheumatoid arthritis, colitis, experimental autoimmune encephalomyelitis (EAE), and late stage of type 1 diabetes." (PMID 33805271, 2021). "Disruption of LTBR signaling could be a new tool for the investigation and potentially the treatment of certain subgroups in autoimmune diseases." (PMID 25405351, 2014). "Accelerated clearance of immunoglobulin-based agents is commonly observed in many rodent autoimmune disease models, and our finding of a reduction in the serum levels of LTβR-Ig as the mice age also points to a possible increased clearance of the fusion protein in these older NOD mice." (PMID 19222863, 2009). "It is hard to prove that LTα1β2 -LTβR signaling is essential for the development of certain autoimmune diseases, since LIGHT-mediated LTβR signaling plays a similar role in some T cell-mediated autoimmune diseases." (PMID 33805271, 2021). "Thus, LTβR dependent growth suppression is involved in regulating the size of secondary lymphoid organs, and might be therapeutically used to eradicate tertiary lymphoid tissues during autoimmune diseases." (PMID 27936003, 2016).
atherosclerosis (10 papers, 2015 to 2025). A disease characterized by the build-up of fatty material and calcium deposition in the arterial wall resulting in partial or complete occlusion of the arterial lumen. "Aortic plaque burden and the quantity of lesional macrophages in atherosclerosis are greatly reduced by LTβR deficiency." (PMID 39707217, 2024). "In mice, LTβR deficiency reduced atherosclerosis, while LIGHT treatment aggravated lesion size." (PMID 34829747, 2021). "Global or VSMC-specific deficiency of LTβR in aged hyperlipidemic ApoE−/− mice demonstrated increased atherosclerotic plaque formation indicating that the VSMC LTβR has the ability to attenuate development of atherosclerosis under some experimental conditions." (PMID 31164888, 2019). "Although the precise role of LTβR in atherosclerosis remains incompletely understood, pharmacological inhibition of LTβR significantly reduces aortic plaque burden and macrophage infiltration in atherosclerotic lesions." (PMID 41268556, 2025). "Investigations in humans have demonstrated increased LIGHT levels in unstable angina and augmented soluble LTβR in atherosclerosis." (PMID 34829747, 2021). "However, given their pro-inflammatory roles in atherosclerosis and disease-associated upregulation, LIGHT, HVEM, and LTβR represent promising candidates for future development as both diagnostic biomarkers and therapeutic targets." (PMID 41268556, 2025). "Notably, LIGHT levels are elevated in coronary disease, clinical heart failure, and unstable angina, while LTβR is increased in human atherosclerosis." (PMID 34829747, 2021). "Likewise, LTβR inactivation has been reported to diminish atherosclerosis, and LIGHT treatment worsened lesion size." (PMID 34829747, 2021). "For example, leukocyte aggregates in the synovium of patients with rheumatoid arthritis (RA) form in close proximity to networks of αSMA+ fibroblastic cells, and LTβR+ aortic smooth muscle cells have been observed in vascular TLS that form in murine models of atherosclerosis." (PMID 27877173, 2016). "However, the role of LTβR in atherosclerosis remains debated." (PMID 41268556, 2025). "The combined activation of TNFRI and LTβR is required for the formation of TLS in both inducible and spontaneous models of atherosclerosis." (PMID 27877173, 2016).
Sjögren's syndrome (10 papers, 2009 to 2025). "In NOD mice, inhibition of MECA-79+ HEV-like blood vessels after treatment with LTβR-Ig is associated with improved function of salivary and lacrimal glands, suggesting that LTβR inhibition may ameliorate disease in human Sjögren’s syndrome." (PMID 33956259, 2021). "Recent research of Sjögren's syndrome reported that the LTβR-Ig fusion protein partially restored salivary flow and reduced glandular inflammation." (PMID 39707217, 2024). "Since the formation and maintenance of functional HEV in secondary lymphoid organs of mice is regulated by the LTBR axis, as well as in TLT in experimental disease models, LTBR is a novel therapeutic target in Sjögren's syndrome." (PMID 22044682, 2011). "In this study, we tested the chimeric antagonist LTBR-Ig, as a possible long-term therapeutic reagent (8-10 week treatments) for KS in Sjogren's syndrome." (PMID 22044682, 2011). "We investigated the effect of blockade of the lymphotoxin-beta receptor (LTBR) pathway on lacrimal-gland pathology in the NOD mouse model of Sjögren's syndrome." (PMID 22044682, 2011). "From 2014 to 2018, significant areas of focus included “Breast cancer”, “Sjogrens syndrome”, “Node like structures”, “Rheumatoid arthritis”, “Lymphoid neogenesis”, “Dendritic cells”, “NF-κB”, “Lymphotoxin beta receptor”, “Antigen”, “B lymphocytes”, and “Autoantibody production”." (PMID 39620224, 2024). "LTβR-Ig fusion protein changed lymphocyte trafficking and reduced inflammatory markers in line with its expected mechanisms of action, but not producing considerable clinical efficacy in rheumatoid arthritis or Sjögren's syndrome." (PMID 39707217, 2024). "Blockade of LTBR pathways may have therapeutic potential for treatment of Sjögren's syndrome." (PMID 22044682, 2011). "Development of mature FRCs from precursor cells in SLO is driven by LTβR signalling, and TLS-forming FRC-like ‘immunofibroblasts’ have been shown to be regulated by LTα1b2 and IL22 in Sjogren’s syndrome." (PMID 39757146, 2025). "The aim of this study was to determine the effects of LTβR pathway blockade on Sjögren syndrome (SS)-like salivary gland disease in non-obese diabetic (NOD) mice." (PMID 19222863, 2009). "However, a human LTβR-Ig fusion protein (Baminercept) failed to produce significant clinical efficacy in RA and Sjögren’s syndrome." (PMID 33956259, 2021).
breast cancer (9 papers, 2015 to 2025). A primary or metastatic malignant neoplasm involving the breast. "Recently, a study found that the combination of anti-VEGFR2 and anti-PD-L1 antibodies induced the generation of endothelial venules(HEVs), which promoted lymphocyte infiltration through the activation of lymphotoxin β receptor (LTβR) signaling in breast cancer and pancreatic neuroendocrine cancers." (PMID 29515799, 2018). "One study demonstrated that successful treatment of combined anti-VEGFR2 and anti–PD-L1 in breast cancer and pancreatic cancer was correlated with the induction of high endothelial venules (HEV) that resulted in lymphocyte infiltration through activation of lymphotoxin β receptor (LTβR) signaling." (PMID 35096619, 2021). "Treatment with the LTβR agonist or the LTβR ligand LIGHT, which had been targeted to the tumor vasculature by fusing it to a vascular zip code peptide, induced MECA79+ HEVs in various mouse tumor models, including those of breast cancer, neuroendocrine pancreatic tumors, and glioblastomas." (PMID 34484246, 2021).
Autoimmunity (8 papers, 2012 to 2025). The occurrence of an immune reaction against the organism's own cells or tissues. "We assessed key parameters which previously have been associated with systemic inflammation and autoimmunity in LTβR-/- mice." (PMID 34335629, 2021). "Recently, we found that fibroblast‐specific LTβR‐deficient mice displayed signs of autoimmunity against peripheral tissues, similar to systemic LTβR‐deficient mice." (PMID 34096078, 2021). "The fibroblast-specific LTβR-deficient mice displayed signs of autoimmunity against peripheral tissues in a manner that was similar to systemic LTβR-deficient mice." (PMID 33519827, 2020). "Collectively, the autoimmune pathology observed in these individuals phenocopies the autoimmunity seen in murine models deficient in NIK or LTβR signaling, further supporting the indispensable role of NIK within mTECs for the establishment of central tolerance in humans." (PMID 41280889, 2025). "Because the failure in the movement of the positively selected T cells to the medulla results in autoimmunity, this function may be linked to the autoimmune phenotypes observed in LtβR-KO mice." (PMID 22969770, 2012). "To define the role of LTβR signaling in adulthood on autoimmunity and systemic inflammation, we analyzed the liver, lung, and thymus of iLTβRΔ/Δ mice for tissue abnormalities or key autoimmune indicators." (PMID 34335629, 2021). "In summary, our study redefined the role of LTβR signaling in adulthood for organization of lymphoid organs, autoimmunity, homeostasis of innate immune cells and IgA production." (PMID 34335629, 2021). "We next analyzed thymus organization, as impaired negative selection of lymphocytes due to defects in thymus structure was attributed to autoimmunity in LTβR-/- mice." (PMID 34335629, 2021). "Since an autoimmune phenotype in LTβR-/- mice can be due to developmental defects in lymphoid organs and intestinal microbiota composition, the role of LTβR signaling in autoimmunity and systemic inflammation in adulthood remains controversial." (PMID 34335629, 2021). "The fetal thymic stroma transplantation confirmed the requirement of LtβR signaling in the thymic stroma cells for the suppression of autoimmunity." (PMID 22969770, 2012). "Since these defects are imprinted during embryogenesis or early neonatal stages, the role of LTβR in lymphoid tissue maintenance, autoimmunity, homeostasis of innate immune cells, IgA production and immune responses in adulthood remain unclear." (PMID 34335629, 2021). "Furthermore, our results indicate that adult stage LTβR signaling is dispensable for the maintenance of polyclonal IgA responses and autoimmunity." (PMID 34335629, 2021). "Therefore, LTBR hypomethylation not only plays a pivotal role in the ignition of autoimmunity but also is a potential therapeutic target." (PMID 30159339, 2018). "This differs substantially from AIRE deficiency, the prototype disease of thymic dysfunction—as LTβR-deficient patients predominantly present with B cell dysfunction in the absence of IFN-γ–driven chronic inflammation and autoimmunity." (PMID 41280889, 2025). "In contrast to LTβR-/- mice, iLTβRΔ/Δ mice displayed normal thymus structure and did not develop signs of systemic inflammation and autoimmunity." (PMID 34335629, 2021). "Deletion or mutation of RelB, the tumor necrosis factor receptor-associated factor 6 (Traf6), NFκB-inducing kinase (NIK) and the lymphotoxin β receptor (LTβR), leads to defective development of mTECs, reduced or absent medulla and development of autoimmunity." (PMID 24465914, 2014). "Thus, our results suggest that inactivation of LTβR signaling in adulthood does not result in autoimmunity and systemic inflammation." (PMID 34335629, 2021). "However, mice lacking LTβR specifically in TECs do not exhibit signs of autoimmunity, while mice systemically lacking LTβR do, indicating that the key target of lymphotoxin signaling in the context of tolerance induction must be non‐TEC stromal cells." (PMID 34096078, 2021).
Autoimmunity (continued). "Thus, we conclude that inhibition of LTβR signaling in adulthood does not lead to systemic inflammation and autoimmunity." (PMID 34335629, 2021). "Our results suggest that inducible genetic LTβR inactivation during adulthood results in impaired organization of LNs and spleen; homeostasis of neutrophils, NK, and iNKT cells; and generation of mucosal pathogen-specific IgA responses but does not result in autoimmunity." (PMID 34335629, 2021).
melanoma (8 papers, 2007 to 2025). A malignant, usually aggressive tumor composed of atypical, neoplastic melanocytes. "Given the lack of clear mechanism explaining how LTβR affects drug resistance and apoptosis, we aimed to elucidate this gap using an LTβR knockdown system in melanoma cells, where high LTβR expression is correlated with poor survival rate." (PMID 40883295, 2025). "Recent evidence shows that LTBR is mostly expressed on myeloid cells by analyzing melanoma scRNA‐seq data." (PMID 39429877, 2024). "In particular, LTβR expression has been noted in ovarian cancer cells and their CAFs while activation of the LTβR pathway has been previously reported in breast, colorectal, lung, larynx/pharynx, gastric cancers and melanomas." (PMID 31137630, 2019). "The results of the flow cytometry (FCM) assay indicated that the expression of LTβR on the surface of HEVs was lower in the VEGFD-OE group than in the control group, suggesting that VEGFD also induced HEV dedifferentiation in melanoma." (PMID 40693467, 2025).
asthma (7 papers, 2014 to 2023). "Our current data also show that there was a concomitant suppression of ADAM-33, LIGHT, and LTBR, three other mediators known to be associated with the pathogenesis of asthma." (PMID 25642424, 2015). "Insulin decreased mRNA expression of IL-4, ADAM-33, and LTBR (lymphotoxin beta receptor), which are all potentially involved in pathogenesis of asthma." (PMID 26783384, 2015). "We hypothesized that LIGHT and LTβR signaling contribute to severe asthma through induction of IL-8, which promotes accumulation of neutrophils and inflammation in the airway." (PMID 25501580, 2014). "Since LTβR is expressed on various airway epithelial cells, the LTβR signaling pathway might represent a new therapeutic target for severe asthma." (PMID 25501580, 2014). "Since IL-4, LIGHT, LTBR, TGFβ, MMP-9, and NO are key mediators involved in the pathogenesis of allergy and asthma, the increase in their expression may contribute to the increased vulnerability and risk of asthma in the obese." (PMID 25642424, 2015). "By the fact that insulin infusion suppresses the expression of IL-4, ADAM-33, LIGHT, and LTBR and the plasma concentrations of NOM and MMP-9, the efficacy of insulin in the treatment of asthma needs to be assessed." (PMID 25642424, 2015). "With LTβR knockout mice, their recent work demonstrated that AHR and airway smooth muscle (ASM) mass reduced in the absence of LTβR in an allergen-induced asthma model and that the signaling pathway involved the interaction of LIGHT-LTβR, instead of LIGHT-HVEM." (PMID 37397546, 2023).